BRCA2 (BRCA2 DNA repair associated)
Diseases named in the same sentence as BRCA2 in open-access papers (continued):
Sharing a sentence is not in itself a finding about the gene and the disease.
cancer (continued). "In carcinomas from Patients A, G and M with high HRD scores, BRCA1 and/or BRCA2 mRNA were markedly downregulated by RNA-sequencing analysis and qRT-PCR (data not shown)." (PMID 25916844, 2015). "Carcinomas from Patients O, P and E may be in the earliest stages of this transformation and have not yet undergone transition toward the diploid state with a high frequency of LOH despite strong evidence of HR inactivation in Patient P (homozygous frameshift mutation of BRCA2)." (PMID 25916844, 2015). "Thus, there is little convincing evidence that heterozygosity for these Brca2 mutant alleles creates a DNA repair defect that could explain heightened cancer predisposition, although the possibility has not yet been conclusively excluded." (PMID 24268522, 2014). "Among these 51 cancer genes, we find BRCA1 and BRCA2 that are multifunctional proteins playing a major role in DNA repair processes." (PMID 24550935, 2014). "Germline mutations in its interacting partner BRCA2 are known to predispose to cancers of the breast, ovary and pancreas, as well as confer a moderate increased risk of CMM (relative risk of 2.6), suggesting by association that PALB2 may also play a role in tumour development in these cancer types." (PMID 24949998, 2014). "We believe that methods for stratifying the likelihood of carrying a BRCA1 and BRCA2 mutation that is independent of family history are important, particularly in the Asian context, because the familial and social stigma associated with cancer makes accurate family-history reporting challenging." (PMID 23116406, 2012). "coli genes as well as two human cancer genes (BRCA1 and BRCA2) in three independent stages and different multiplexing folds on the SOLiD system." (PMID 22913592, 2012). "The remaining 1492 were members of a family in which an affected woman (i.e., with a previous diagnosis of cancer) had undergone testing for BRCA1 and BRCA2." (PMID 19088722, 2009). "There is compelling data that pathogenic mutations in BRCA1 result in a distinct tumour phenotype, whereas more subtle similarities are seen between BRCA2 cases and among familial non-BRCA1/BRCA2 cancers." (PMID 19094228, 2008). "In contrast to BRCA1 tumours, the BRCA2 tumours diagnosed in patients 50 years or older were more often ER- (52.6% vs 25.6%, P = 0.02) and PR- (80.0% vs 54.4%, P = 0.036) than non-BRCA1/2 cancers among the same age group." (PMID 15987451, 2005). "In this study, the familial non-BRCA1/2 cancers were diagnosed at a marginally younger age than those among unselected cases, and were more often of lower grade than the control cancers or BRCA1 and BRCA2 cancers." (PMID 15642173, 2005). "In comparison with BRCA1 or BRCA2 cancers, familial non-BRCA1/2 cancers represented a much greater number of ER-positive and PgR-positive cases; however, in comparison with the unselected control group they were more receptor-negative." (PMID 15642173, 2005).
cancer (continued). "We examined the hypermethylation status of a panel of 5 normally unmethylated tumor suppressor or cancer genes: FHIT, FANCF, Cyclin-D2, BRCA2 and RUNX3 in 25 ovarian GCTs and ovarian cell line DNAs using the MSP assay." (PMID 15574200, 2004). "Even though the age of cancer diagnosis varies, patients with BRCA mutations seem to have a lower age of cancer diagnosis when compared to the general population of patients, with the mean age of cancer diagnosis being around 51 years for BRCA1 patients and 61 years for BRCA2 patients." (PMID 40869932, 2025). "Our work also confirmed that another thymidine analogue, EdU, is cytotoxic and induces DNA damage in mammalian cancer cells, independent of BRCA2 status." (PMID 41347092, 2025). "Male BRCA2 PV carriers had elevated CBC (SIR, 431 [95% CI, 48.5 to 1,559]), pancreatic (SIR, 20.2 [95% CI, 4.07 to 59.1]), and prostate (SIR, 4.46 [95% CI, 1.79 to 9.19]) cancer SIRs." (PMID 39475295, 2025). "In comparison, our study is a population based cohort where BRCA2 carriers were systematically identified in all participants, where the vast majority of carriers did not report a family history of cancer." (PMID 40462315, 2025). "The P75 was consistently higher in BRCA2 PV carriers than noncarriers for each type of these 10 cancers." (PMID 40462315, 2025). "The discovery of pathogenic variants (PVs) in the Breast Cancer Gene 1 (BRCA1) and Breast Cancer Gene 2 (BRCA2) genes, which account for approximately 10–15% of non-mucinous epithelial ovarian cancers (EOC), has revolutionised the management of this disease." (PMID 40805236, 2025). "Carriers of BRCA2 PVs had a significantly higher prevalence of any cancer (41.80%) compared to noncarriers (22.39%), HR (95% CI) was 2.29 (2.12–2.47), p < 0.001." (PMID 40462315, 2025). "BRCA2 PV carriers were at increased CBC (HR, 2.40 [95% CI, 1.70 to 3.40]), ovarian (HR, 12.0 [95% CI, 6.70 to 21.5]), and pancreatic (HR, 3.56 [95% CI, 1.34 to 9.48]) cancer risks." (PMID 39475295, 2025). "Similar to PD-L1+ cancer cells, PD-L1+ macrophages are enriched with a greater number of CD8+ PD-1+ T cells within a short distance, which is particularly common in BRCA2-mutated HGSOC cases but absent in HRP tumors." (PMID 40830526, 2025). "Ten patients had germline mutations affecting cancer predisposition genes not typically linked to WT: CHEK2 in 4 children, and BLM, BRCA2, CDKN2A, FMN2, PIK3C3, and STK11 in one patient each." (PMID 40340749, 2025). "This phase Ib trial investigates the side effects of INO-5401 with or without INO-9012 and evaluates a new method of administering vaccines (electroporation) in adult cancer and non-cancer patients with BRCA1 or BRCA2 mutations." (PMID 40243654, 2025). "As an example, one of our samples without known alteration but with a family cancer history, had two deep intron variants predicted, in silico, as creating new alternative splicing sites in BRCA1 (new 5′ splicing site), and BRCA2 (new 3′ splicing site)." (PMID 39783935, 2025). "” Unlike the dramatic destabilization following her mother’s cancer diagnosis and her own BRCA2 carrier status, Patricia fully embodied a new identity, enabling her to look toward the future with hope and confidence." (PMID 39050256, 2024). "The PCAT1 ncRNA is known to repress BRCA2, activate MYC, promote cell proliferation, and is upregulated in prostate, colorectal, and other cancers." (PMID 38981681, 2024).
cancer (continued). "Pol θ has been shown to conduct microhomology-mediated end-joining (MMEJ) (also known as theta-mediated end-joining or TMEJ) in the absence of functional BRCA1 and/or BRCA2 in cancer cells." (PMID 38666816, 2024). "Mutations in BRCA1, BRCA2, and non-BRCA cancer susceptibility genes accounted for 34.9% (n = 213), 31.6% (n = 193), and 35.1% (n = 214), respectively." (PMID 38355628, 2024). "Interestingly, E7820-mediated double-strand breaks in DNA were increased in tumors with BRCA2 dysfunction, and knockdown of BRCA1/2 transcripts or knockout of ATM, ATR, or BAP1 sensitized cancer cells to E7820." (PMID 38789724, 2024). "Although cells with WT and functional BRCA1/BRCA2 activate the canonical Wnt/β-catenin–dependent signaling pathway upon Wnt3A treatment, cancer cells that lose BRCA1 function activate the noncanonical β-catenin–independent pathway instead." (PMID 39028933, 2024). "Based on their findings, almost one-third of the under-examination individuals had at least one type of cancer, with prostate cancer being the most common (2 patients in the BRCA1 group and 11 patients in the BRCA2 group), followed by breast, skin and urothelial cancer." (PMID 38534919, 2024). "Dose–response experiments were performed using the BRCA1 and BRCA2 wild-type breast (MDA-MB-231 and MCF-7) and ovarian (HEY-T30 and SKOV-3) cancer cell lines to determine the differences in their drug sensitivity and the concentrations appropriate for the drug combination experiments." (PMID 39273190, 2024). "In our meta-analysis, we identified six genes with high mutation prevalence in brain metastases, of particular interest for their potential role in brain metastatic process and resistance to first-line anti-cancer drugs: ESR1, ERBB2, EGFR, PTEN, BRCA2 and NOTCH1." (PMID 36980614, 2023). "The average cumulative lifetime risk of women without a history of cancer (previvors) is about 70% for BC and 44% (BRCA1 variant) or 17% (BRCA2 variant) for OC." (PMID 37845719, 2023). "Interestingly, the trend of specific gene expression observed in NAT was reverse to that of tumour tissue, with the expressions of BRCA2 and XPD genes showing a trend of increasing in the NAT with an increase in cancer stage." (PMID 37113717, 2023). "Compared to BRCA2, the importance of mutationin BRIP1 does not increase the risk of cancer exposure; however, its product isrecognized as a tumor suppressor and also an oncogene protein." (PMID 39430039, 2023). "We observed a trend for stage-dependent decline in BRCA2 gene expression in the tumour tissues of HNSCC patients, while the matched NAT showed the reverse trend of significantly increasing with the progression of cancer stage." (PMID 37113717, 2023). "PARP inhibition was first described in cancer cells with defective BRCA1/BRCA2 protein function, and then clinical trials confirmed the effectiveness of PARP inhibitors as monotherapy in patients with BRCA1(−/−) and BRCA2(−/−) tumors." (PMID 36769087, 2023). "This suggests a mechanism of chemotherapy resistance in BRCA2 and BRCAX cancers, which may be abrogated in BRCA1mut tumours, most likely due to inherent inactivation of RAD21, as BRCA1wt has been shown to be required to activate RAD21 function." (PMID 36831687, 2023). "Evaluation by logistic regression showed that the occurrence of side effects was not affected by PV/LPV gene (BRCA1 or BRCA2), gender, race, age or history of cancer." (PMID 37046302, 2023). "Theoretically, the biological behaviors between biallelic and heterozygous deletion of BRCA2 in cancer progression should be different since BRCA2 function was not completely lost by the heterozygous deletion." (PMID 36645189, 2023).
cancer (continued). "This is similar to recent preclinical studies reporting that inhibiting different tyrosine kinase receptors or their downstream signaling transducers can sensitize cancer cells to PARPis by reducing expression of BRCA1, BRCA2, RAD51, and other HR components, thereby preventing HR repair." (PMID 37550562, 2023). "APC (P), BRCA2 (P), BUB1B (LP), ENG (LP) and MSH6 (P) were identified in patients with cancer." (PMID 36896836, 2023). "Genetics and cancer: This module provides basic information about the risk of developing HBOC-associated cancers with and without the contribution of BRCA1 or BRCA2 pathogenic variants and the modes of inheritance of these variants." (PMID 37760455, 2023). "Several prominent authors published a number of reviews on the hypotheses that may be suitable for the explanation of the remarkable tissue specificity of early cancers (HBOC) in BRCA1 and BRCA2 heterozygous carriers." (PMID 38275383, 2023). "At first, BRCA1 and BRCA2 mutations were identified as biomarkers in HRD, but there still exists some HRD cancer without BRCA1/2 mutations, indicating that some other HR-related genes would potentially affect PARPi sensitivity." (PMID 37476378, 2023). "Significant disturbances in the mechanism of DSB DNA repair in the absence of fully functional BRCA1 or BRCA2 make cancer cells particularly sensitive to PARP inhibitors, especially in the case of LOH." (PMID 36902416, 2023). "The incidences of BRCA1 and BRCA2 carriers among relatives with 1, 2, and ≥3 cancer types were significantly higher than non-carriers." (PMID 36861435, 2023). "The ability of PARPi to selectively eradicate HR-deficient cancer cells was first illustrated in cells lacking HR components BRCA1 and BRCA2 and provided the basis for the clinical development of PARPi." (PMID 37609662, 2023). "Cancer cells lacking functional BRCA1 or BRCA2, critical players in homologous recombination repair, are more sensitive to PARP inhibition." (PMID 36978917, 2023). "Previous research has shown that many human cancers exhibit BRCA-like mutational signature without harboring any BRCA1, BRCA2, or PALB2 mutations." (PMID 37032811, 2023). "In addition to BRCA1 and BRCA2, many other HRR mediators (ATM, BRIP1, CHEK2, NBS1 or RAD51C) are frequently defective in cancer." (PMID 37298484, 2023). "The first were tightly regulated, through MELK, BRCA2, KIF14, BUB1, and TOP2A, by five TFs (NFE2L3, RUNX1, RUNX2, BHLHE40, and the aging cancer-specific SOX11), two LncRNAs (ST7OT1 and CDKN2BAS), and four miRNAs (miR-21-5p, miR-363-3p, miR-873-5p, and miR-138-1-3p)." (PMID 37191407, 2023). "The remaining most frequent mutated cancer driver genes found in early-stage samples (KMT2C, ALK, BRCA2, GRM, ATM, and BRCA1) were not among those found to be the most frequently shared in late-stage samples (MUC16, CSMD3, KNT2C, NF1, LRP1B, SPEN, and TRRAP)." (PMID 37446001, 2023). "AURORA-A, the expression of which was increased in the pathway of molecular mechanism of cancer after 1 h, 24 h and 8 days of TPA treatment, regulates genomic instability and tumorigenesis through cell cycle dysregulation and BRCA2 suppression." (PMID 35328637, 2022). "Two subsequent studies determined the extensive transcriptional characteristics of innate immune genes based on the cGAS–STING pathway in cancer cells lacking BRCA1 or BRCA2." (PMID 36613695, 2022). "Neither personal history of a cancer diagnosis nor having undergone risk-reducing surgery differed according to the genetic variant (i.e., BRCA1 vs. BRCA2)." (PMID 35326645, 2022). "Although more cancer-risk genes were considered and their cohort was not limited to BC, 74.5% (287 of 385) were also carriers of variants in BRCA1 or BRCA2 genes." (PMID 36003761, 2022). "The ABL1-I418T, PIK3CB-R231H, CHEK2:c.-4C > T, BRCA2-P3292L, ABL1-E459G, PRPF8-G1796R, PHF6-R274Q, WT1-R435X and ATM-C117Y variants were potentially important cancer variants which were not actionable." (PMID 35896598, 2022).
cancer (continued). "In addition, BRCA2 acts as a tumor suppressor in mitotic HR, and HSF2BP can bind to BRCA2 and mediate its recombination localization, thereby promoting cancer development by interfering with the mitotic HR pathway." (PMID 35435115, 2022). "Consistent with their different roles in HR repair, BRCA2-type cancers do not display these small TDs, but very specifically harbor small (<10 kb) deletions." (PMID 35159019, 2022). "The rate of PrCa in BRCA1 variant carriers (8.6%) was twice that of BRCA2 variant carriers (3.8%), screening all men using annual PSA and DRE (neither PSA screening threshold or cancer characteristics reported)." (PMID 33486571, 2022). "One of the biggest limitations that remains is that large datasets of BRCA1- and BRCA2-mutant cancer patients treated with PARPi are not yet broadly available." (PMID 36568963, 2022). "MUS81 defects sensitize cells to various genotoxic chemicals, and it was recently shown that inhibition of MUS81 sensitizes HR-proficient cancer cells to the PARP1 inhibitor, olaparib, an agent commonly used to treat cancers with HR defects, such as BRCA1- and BRCA2-defective breast cancers." (PMID 36203968, 2022). "After learning their genetic status, group 1 participants described becoming “more attuned” to their cancer risks as they had become “a real thing”, not just an abstract concept (Sharon, 75 years, BRCA2)." (PMID 35887609, 2022). "This may be attributed to a novel role in the motility and migration of cancer cells that were proposed for cytoplasmic and membranous localised BRCA1 and BRCA2 proteins." (PMID 34045664, 2022). "Several studies demonstrated that unlike normal cells, RAD52 is required for the survival of cancer cells with loss-of-function mutation in genes such as BRCA1, BRCA2, PALB2, and RAD51 paralogs." (PMID 35463312, 2022). "We compared the carrier frequencies of our candidate variants in different FC groups comprised of cancer cases, regardless of BRCA1 or BRCA2 pathogenic variant status, and cancer-free controls." (PMID 35565380, 2022). "Recombination mediator proteins have come into focus as promising targets for cancer therapy, with synthetic lethal approaches now clinically validated by the efficacy of PARP inhibitors in treating BRCA2 cancers and RECQ inhibitors in treating cancers with microsatellite instabilities." (PMID 35327990, 2022). "In addition, classic cancer driver genes identified in other cancers were also identified as SMGs in this study, including ATM (3.45%, 12/348), BRCA2 (2.01%, 7/348), and MLLT4 (2.01%, 7/348)." (PMID 35650238, 2022). "More recent studies reported higher prevalence of DCIS incidentally diagnosed during risk reducing mastectomy in BRCA1 and BRCA2 PSV carriers—Kauff and coworkers compared BRCA carriers with age- and race-matched controls without a known cancer predisposition." (PMID 36349178, 2022).